PGK1 (phosphoglycerate kinase 1)
Diseases named in the same sentence as PGK1 in open-access papers (continued):
Sharing a sentence is not in itself a finding about the gene and the disease.
tumor (continued). "Reducing or inhibiting the PGK1 signaling pathway could significantly enhance radiosensitivity and inhibit tumor growth, which is a rational method to improve the outcome of radiotherapy and chemotherapy just by PGK1 silencing." (PMID 37408007, 2023). "The ability of PGK1 to promote tumour proliferation may be partly due to its involvement in the positive regulation of PTMs." (PMID 37723547, 2023). "In addition to regulating glycolytic metabolism, PGK1 has many characteristics of oncogenes, promotes tumour cell proliferation, migration and invasion and is involved in the initiation of autophagy and DNA replication in cancer cells." (PMID 37723547, 2023). "The qRT-PCR tests showed that PGK1 was highly expressed in tumor tissues." (PMID 36949536, 2023). "Therefore, it is probable that overexpression of PGK1 will slow tumor growth by reducing angiogenesis." (PMID 36837801, 2023). "PGK1 not only provides energy required for tumor growth, but also act as a protein kinase." (PMID 37449059, 2023). "High intracellular expression of PGK1 leads to tumour cell proliferation." (PMID 37723547, 2023). "Disruption and effective anti-GBM agents were triggered in the hypoxic region, leading to efficient tumor suppression by using phosphoglycerate kinase 1 (PGK1) silencing to enhance paclitaxel-induced chemotherapy and sensitize hypoxic GBM cells to ionizing radiation." (PMID 37408007, 2023). "The PGK1 promoter is methylated in multiple types of tumour cells." (PMID 37723547, 2023). "Whether PGK1 can promote tumour occurrence by inducing autophagy in cancer under normal oxygen conditions or under normal nutritional conditions is still under study, and such studies are expected to provide new insights for targeted cancer treatment." (PMID 37723547, 2023). "Patients with greater MVIH expression in their tumor tissues showed reduced PGK1 serum levels." (PMID 35154157, 2022). "The results showed that PGK1 was highly expressed in both tumor cells and immune cells." (PMID 36358653, 2022). "Meanwhile, in a few types of cancer, including KICH, PGK1 mRNA expression was low in tumor tissues." (PMID 36358653, 2022). "The “Gene” component analysis revealed that, whereas PGK1 expression had no discernible relationship with tumor purity, it was strongly linked to infiltrating levels of macrophages, neutrophils, and dendritic cells in LUAD." (PMID 36358653, 2022). "In addition, immunohistochemistry of the tumor sections showed that the expression levels of key glycolytic enzymes PGK1 and LDHA decreased via the treatment with berberine." (PMID 35559258, 2022). "We used TISIDB to assess the relations between the abundance of tumor-infiltrating lymphocytes (TILs) and expression of PGK1 in order to examine which kinds of TILs might be regulated by PGK1." (PMID 36358653, 2022). "In addition, through GSEA analysis of the transcriptome data from the GSE6344 dataset and GSE15641 dataset, we found that PGK1 expression was positively correlated with tumor hypoxia in KIRC." (PMID 35121728, 2022). "In a word, considering gene expression associations of PGK1 with glycolysis-related enzymes, and PGK1 upregulation related to KIRC occurrence, we speculated PGK1-invovled glycolysis sustained tumor cell growth and survival for KIRC progression." (PMID 35121728, 2022). "In addition, it has also been reported that the functions of PGK1 inside and outside cells are different, and the high expression of PGK1 in cells leads to the proliferation of tumor cells." (PMID 36358653, 2022). "In addition, similar to the results in vitro, PRAS40 phosphorylation was downregulated remarkably in PGK1-knockdown tumor xenografts." (PMID 35058442, 2022). "Meanwhile, SMAD4 inactivation in PAAD could promote upregulated expression of PGK1 and enhance glycolysis and tumor invasiveness." (PMID 35795552, 2022). "Thus, the limited secretion of Pgk1 from tumor cells would favor the angiogenesis and growth of tumors." (PMID 35456967, 2022).
tumor (continued). "The moonlighting protein kinase activity of PGK1 can autophosphorylate PGK1 at Y324 and autoactivate PGK1, and the deficiency or mutation of PTEN, which functions as a protein phosphatase to dephosphorylate PGK1 pY324, in tumor cells enhances the PGK1-promoted Warburg effect." (PMID 39872073, 2022). "Finally, higher PGK1 expression indicated significant correlations to immune checkpoints, TMB (tumor mutation burden), and high response to immunotherapy." (PMID 36358653, 2022). "Since the loss of SMAD4 expression is responsible for increased glycolysis in cancer cells due to the overexpression of glucose transporters, the loss of SMAD4 in PDA cells also led to an increased expression of PGK1, enhancing glycolysis and more aggressive tumor progression." (PMID 33804240, 2021). "The pan‐cancer analysis indicated that PGK1 may activate multiple immune genes and interfere with the tumor environment in 32 types of cancer." (PMID 34668665, 2021). "Therefore, PGK1 plays a key role in the ATP synthesis of cancer cells and the promotion of tumor progression." (PMID 34277429, 2021). "The Aberrant expression of PGK1 in various tumor tissues, peripheral blood and saliva of patients, could promote rapid tumor growth and progression." (PMID 34291087, 2021). "PGK1 is highly expressed and promotes the proliferation of tumor cells." (PMID 34536269, 2021). "PGK1 overexpression impaired the inhibitory effect of PTCSC3 in tumour progression." (PMID 34337858, 2021). "However, little is known about the relationship between PGK1 and the tumor immune microenvironment in TSCC." (PMID 34668665, 2021). "However, more details of PGK1 mediated tumor metabolism related signaling pathways need to be further investigated in future researches." (PMID 34291087, 2021). "Acetylation at different lysine residues in PGK1 was able to positively or negatively regulate its enzymatic activities, which initiated or altered some signaling pathways, such as metabolism or autophagy, leading to tumor formation or progression." (PMID 34712204, 2021). "In addition to the important role in glycolysis, PGK1 was also proved to have critical function in tumor progression." (PMID 34291087, 2021). "PGK1 inhibitors have been shown to induce cell apoptosis and to inhibit tumor cell adhesion and metastasis, whose pharmacological effects implied that PGK1 may have similar regulations in VSMC proliferation and migration." (PMID 34445528, 2021). "To further investigate whether PTCSC3 performs an anti‐tumour function via PGK1, we overexpressed PGK1 in PTCSC3‐overexpressing TPC‐1 and BCPAP cells, and their protein expression was confirmed by Western blot." (PMID 34337858, 2021). "Therefore, PGK1 is a potential target of tumor therapy and an intensely studied molecule in tumor therapy research." (PMID 34291087, 2021). "In addition, increasing evidence has indicated that PGK1 participates in the hallmarks of cancer, including angiogenesis, DNA replication and repair in mammalian nuclei and tumor invasion and progression." (PMID 33747900, 2021). "In addition, miR-16-1-3p negatively correlated with tumor size, nodal status, and grade, and PGK1 positively correlated with tumor size, nodal status, and grade." (PMID 33344462, 2020). "However, multiple studies have suggested that in metastatic tumor cells, PGK1 plays a completely contrary role." (PMID 32241274, 2020). "Moreover, the ability of anti-miR-16-1-3p to promote tumor growth was compromised by PGK1 knockdown." (PMID 33344462, 2020). "Phosphoglycerate kinase 1 is one of the key enzymes in tumor glucose metabolism." (PMID 33344462, 2020). "Taken together, these results suggest that PGK1 is crucially involved in the glycolytic switch, cytosolic glycolysis, lactate production, extracellular acidification, autophagy and resistance to anoikis of tumour cells shed into the peritoneal cavity." (PMID 31198853, 2019).
tumor (continued). "This is mediated by chemokine homing from omental adipokine release and tumor PGK-1 expression." (PMID 31683709, 2019). "In all types of cancer, the PGK1 mRNA levels in tumor and matched normal tissues were approximately 212 to 214 times higher than those of PGK2, which could hardly be detected." (PMID 31578148, 2019). "This indicates that HPRT1 and PGK1 may have a grade dependency, and could serve as biomarkers for tumor aggressiveness." (PMID 30679932, 2019). "The results indicated that prioritized proteins, CSTB, NDRG1, PGK1, and ITGAV, may play a relevant biological role in tumor progression, since they were potentially associated, directly or indirectly, with patient prognosis." (PMID 30185791, 2018). "In addition PGK1, when secreted in extracellular compartment by tumor cells, binds plasmin thus permitting the cleavage of plasminogen in order to generate the vascular inhibitor angiostatin." (PMID 29995887, 2018). "In addition, in the IHC analysis of neoplastic island proteins, LTA4H and PGK1 showed peripheral staining in neoplastic cells and were also detected in cells in the tumor stroma, such as inflammatory cells." (PMID 30185791, 2018). "The majority of proteins (ACTR2, CSTB, LTA4H, PGK1, NDRG1, FSCN1, ITGAV, THBS2) significantly associated with clinical parameters showed lower expression in the ITF of the tumor stroma or neoplastic islands, with the exception of COL6A1, COL1A2, S100A8, S110A9, and MB." (PMID 30185791, 2018). "Additionally, compared to control groups, sh-PGK1 decreased tumor proliferation indices by Ki-67 expression (p < 0.01)." (PMID 28749413, 2017). "In addition, PGK1 can decrease the secretion of angiostatin as a disulphide reductase and promote tumor angiogenesis." (PMID 28903403, 2017). "The ubiquitous overexpression of PGK1 in our 100 tumor samples supports the hypothesis of the important role played by this protein in tumorigenesis." (PMID 28686225, 2017). "Furthermore, we performed tail vein injecting assay (n = 6) in nude mice to evaluate the effect of PGK1 in tumor metastasis in vivo." (PMID 28749413, 2017). "Moreover, lncRNA MVIH activates tumor-inducing angiogenesis by inhibiting the secretion of phosphoglycerate kinase 1 (PGK1)." (PMID 29228655, 2017). "Indeed, MVIH expression in the primary tumor inversely correlated with PGK1 levels in serum of HCC patients." (PMID 26131450, 2015). "The group could promote tumor growth and intrahepatic metastasis in vivo and in vitro by inhibiting phosphoglycerate kinase 1 (PGK1) secretion." (PMID 25119862, 2014). "This makes PGK1 an interesting independent indicator for tumor cell dissemination." (PMID 24376734, 2013). "Here, high levels of PGK1 seem to be essential for tumor growth and metastasis." (PMID 24376734, 2013). "MnSOD exhibited a tendency to increase in the tumor tissues of three patients (Cases A, C, and D), but a relative decrease was also observed in Case B. As for PGK-1, a significant relationship between fold changes in protein expression and the pathological grading of tumors was hardly observed." (PMID 17187689, 2006). "Several potential mechanisms may contribute the role of PGK1 in tumor progression." (PMID 40771921, 2025). "We investigated whether miR-185-3p exerts tumor-suppressive effects through PGK1." (PMID 40051638, 2025). "Significantly, when the tumor model with PGK1 knockdown was treated with lapatinib, it exhibited a more pronounced tumor regression compared to the PGK1-knockdown-only group, suggesting that the expression level of PGK1 influences the in vivo tumor response to lapatinib." (PMID 40786054, 2025). "To determine whether PGK1 K63 ubiquitination-induced lactate accumulation affects tumor angiogenesis, we performed endothelial cell migration and tube formation assays to test whether PGK1 silencing would recapitulate the effect of TRIM8 suppression on angiogenesis." (PMID 41184227, 2025).
tumor (continued). "Additionally, PGK1 may interact with immune cells within the tumor microenvironment to modulate immune responses and create a more favorable environment for tumor growth." (PMID 40771921, 2025). "Therefore, we believe that PGK1 mediates lapatinib resistance in N87 cells through two factors: on the one hand, PGK1 acts as a glycolysis enzyme involved in lactate production, mediating the survival of tumor cells exposed to lapatinib." (PMID 40786054, 2025). "Furthermore, PGK1 plays a vital role in modulating the tumor microenvironment." (PMID 38993561, 2024). "In addition, studies have demonstrated that PGK1 participates in tumor development." (PMID 39770478, 2024). "In addition, PGK1 enhances glucose uptake and lactate production in tumor cells." (PMID 36949536, 2023). "Furthermore, we uncovered that miR-4458 acted as a tumor inhibitor in BC through PGK1." (PMID 36949536, 2023). "In addition, we found that increased levels of PGK1 phosphorylation, but not PGK1 protein levels, were associated with tumor weight in xenograft TE-8 cells." (PMID 36966136, 2023). "The participation of phosphoglycerate kinase 1 in this network was intriguing; indeed, apart from the canonical metabolic role, it is involved in multiple biological processes, including angiogenesis, DNA replication and repair, the proliferation and metastasis of tumor cells, and cell invasion." (PMID 37834061, 2023). "Due to this, tumor growth may depend on a finely tuned balancing act between the hypoxic response, which is required to produce pro-angiogenic factors and events necessary for anaerobic metabolism (such as PGK1)." (PMID 36837801, 2023). "Furthermore, it was proposed to use PGK1 as a therapeutic target for tumours." (PMID 37449059, 2023). "Depletion of NEAT1 markedly inhibited tumor growth in mice, while PGK1 could reverse this effect." (PMID 35123484, 2022). "Therefore, we further validated the correlation between PGK1 and tumor-infiltrating cells." (PMID 34277429, 2021). "Moreover, PGK1 localization could also be responsible for different behaviors: cytoplasmic PGK1 might act to promote growth of the primary tumor and instead nuclear PGK1 could enhance the spreading of metastasis." (PMID 33804240, 2021). "Furthermore, TAM-derived IL-6 induces the phosphorylation of PDPK1-mediated PGK1 threonine (T) 243 in tumor cells, to facilitate a PGK1-catalyzed reaction toward glycolysis by altering substrate affinity, which upholds PDAC initiation in a metabolic regulation way." (PMID 33505964, 2020). "However, whether the newly identified protein kinase function of PGK1 applies to other cancer types and the relationship between PGK1 kinase activity and tumor progression remain unknown." (PMID 31578148, 2019). "MVIH could activate tumor-inducing angiogenesis by inhibiting the secretion of phosphoglycerate kinase 1 (PGK1); for example, MVIH expression was negatively correlated with the PGK1 level and positively correlated with the micro-vessel density in 65 cases of HCC." (PMID 31906046, 2019). "Future studies could evaluate the CSTB, PGK1, LTA4H levels in saliva according to recurrence and/or second primary tumor, which were relevant clinical data associated with their expression in the tissues and are also clinical challenges for therapeutic management in OSCC." (PMID 30185791, 2018). "The changes in the catalytic properties and in the stability of the PGK1 variants, mainly due to the local changes evidenced by the X-ray structures, suggest also changes in the functional role of PGK to support the biosynthetic need of the growing and proliferating tumour cells." (PMID 29995887, 2018). "Notably, knocking down PGK1 obviously inhibited tumor growth in vivo (p < 0.01)." (PMID 28749413, 2017).
tumor (continued). "Interestingly, pathway analysis revealed that tumours 1203/1204 demonstrated significant enrichment for the term glycolysis/gluconeogenesis, reflecting increased tyrosine phosphorylation of several metabolic enzymes, including Pgam1, Pkm2 and Pgk1." (PMID 25200860, 2014). "Here, we showed that PGK1 increases ESCC cells tumourigenicity, and promotes EMT and tumour metastasis ability." (PMID 40534132, 2025). "Zhu reported that a MYC-responsive lncRNA called gLINC enhances cancer glycolysis and tumor formation by assembling glycolytic enzymes such as ENO1 and PGK1, PKM2, and LDHA." (PMID 41361062, 2025). "11,94 By upregulating phosphoglycerate kinase 1 (PGK1), ACTL6A enhances glycolysis triggered by follicle-stimulating hormone (FSH), promoting tumor growth and metastasis." (PMID 40657395, 2025). "For instance, NEAT1 promotes breast cancer progression by forms a scaffold bridge for the assembly of PGK1/PGAM1/ENO1 complexes, yet other studies describe tumor-suppressive functions of NEAT1 in different contexts." (PMID 41361062, 2025). "Taken together, these results demonstrated that emodin inhibited tumor growth as well as NAT10 and PGK1 expression in vivo." (PMID 41426311, 2025). "Mechanistically, PGK1 promotes metastasis by interacting with HIV Tat-specific factor 1 (HTATSF1) involved in RNA metabolism, affecting multiple genes in tumour progression." (PMID 41154605, 2025). "Among the 7 HRGs included in the hypoxia risk score model constructed in this study, these 6 genes (LDHA, PGK1, PFKP, DCN, LOX, FBP1) have been extensively reported in previous studies for their roles in tumor hypoxia response and progression." (PMID 40464853, 2025). "To further explore the regulatory effect of PGK1 in ESCC cells under hypoxia condition, we then conducted CCK8, transwell, tumour sphere, and ELDA assays on ESCC cells after hypoxia treatment." (PMID 40534132, 2025). "PGK1 and SLC2A1 plays an important role in this phenomenon to promote the increased glycolytic rate of tumor cells." (PMID 40821990, 2025). "Seven GRPGs (PIM2, PGK1, ADPGK, YWHAZ, PTK2, PGAM1, and VDAC1) were significantly upregulated in the TCGA-BRCA tumor tissues." (PMID 40046063, 2025). "Using such approaches, researchers have detected the upregulated expression of various key glycolytic enzymes, such as hexokinase 2 (HK2), phosphoglycerate kinase 1 (PGK1), aldolase, and lactate dehydrogenase A (LDHA), in multiple tumor cell types." (PMID 40313939, 2025). "In this study, we discovered that ACT001 releases MCL, which directly targets and inhibits PGK1, revealing a novel mechanism through which ACT001 modulates tumor metabolism, tumor immune microenvironment (TIME), and cancer progression." (PMID 40016971, 2025). "It is worth mentioning that several reports have shown elevated levels of these gluconeogenesis-related genes, especially ENO1, PGK1, and PKM, in tumor tissues." (PMID 40821334, 2025). "This study demonstrated that the PGK1 positive expression rate in PTC cancer tissues is higher than that in adjacent tissues, which is consistent with the key role of PGK1 in the tumor glycolytic process." (PMID 40771921, 2025). "Multiple studies have shown that PGK1 expression is significantly upregulated in various BRCA subtypes and is closely related to tumor malignancy and prognosis." (PMID 40496561, 2025). "What’s more, wild-type (Flag-PGK1-WT) and constructed Flag-PGK1-R206K mutant HCT116 cells were also subcutaneously transplanted into nude mice to detect the tumor formation." (PMID 38402202, 2024). "CCL5 and CCL18 upregulate various glycolysis-promoting factors, including hexokinase 2 (HK2), phosphoglycerate kinase 1 (PGK1), glucose-6-phosphate dehydrogenase (G6PD), and pyruvate kinase, further facilitating tumor progression." (PMID 38714539, 2024). "We selected 4 candidate genes (PCSK9, SGPP1, PGK1 and FOXM1) reported to be closely involved in tumour progression and radioresistance for further analysis." (PMID 39548064, 2024).